MTG1 (mitochondrial ribosome associated GTPase 1)
Description:
Plays a role in the regulation of the mitochondrial ribosome assembly and of translational activity. Displays mitochondrial GTPase activity.
Synonyms: GTPBP7; GTP
Tractability: Small molecule: a structure with a bound ligand is known. Antibody: UniProt places it where antibodies can reach, with high confidence. PROTAC: ubiquitination databases record sites on it; its protein half-life has been measured.
Gene: Protein-coding gene on chromosome 10 (133,394,094 to 133,422,520, forward strand). Ensembl gene ENSG00000148824.
Subcellular location: Mitochondrion inner membrane
Subcellular location (Human Protein Atlas): Mitochondria
Gene Ontology:
Molecular function: GTPase activity; protein binding; GTP binding
Biological process: mitochondrial large ribosomal subunit assembly; regulation of mitochondrial translation; regulation of respiratory system process
Cellular component: mitochondrial inner membrane; mitochondrial matrix; mitochondrial ribosome; mitochondrion
Genetic constraint (gnomAD): Loss-of-function variants: 29 observed, 36.44 expected, observed/expected ratio (o/e) 0.8, 90% interval 0.59 to 1.09. The synonymous counts are far from expectation, so gnomAD's model fits this gene poorly and the ratio says little. Missense variants: 508 observed, 433.59 expected, observed/expected ratio (o/e) 1.17, 90% interval 1.09 to 1.26. Synonymous variants: 214 observed, 172.95 expected, observed/expected ratio (o/e) 1.24, 90% interval 1.11 to 1.39.
Homologues: Orthologues: pig MTG1 (83% identical), dog MTG1 (82% identical), guinea pig MTG1 (82% identical), rat Mtg1 (81% identical), rabbit MTG1 (80% identical), mouse Mtg1 (79% identical), chimpanzee MTG1 (76% identical), tropical clawed frog mtg1 (64% identical), zebrafish mtg1 (44% identical), Drosophila melanogaster CG17141 (43% identical), Caenorhabditis elegans mtg-1 (35% identical). Paralogues in human: GNL3L (25% identical), GNL3 (24% identical), GNL2 (23% identical), LSG1 (20% identical), GNL1 (19% identical), NOA1 (18% identical).
Diseases named in the same sentence as MTG1 in open-access papers:
MTG1 is named in the same sentence as 13 diseases in open-access papers, as found by Europe PMC text mining. Sharing a sentence is not in itself a finding about the gene and the disease. The quoted sentences say what the papers report.
cardiomyopathy (2 papers, 2021 to 2022). A disease of the heart muscle or myocardium proper. "In contrast, MTG1 deficiency exacerbated pressure-overload-induced mitochondrial dysfunction and cardiomyopathy in MTG1 knockout (KO) mice, which was significantly attenuated with the treatment of N-acetyl-L-cysteine, a powerful antioxidant." (PMID 35624741, 2022).
autism (1 paper, 2016). Persistent deficits in social interaction and communication and interaction as well as a markedly restricted repertoire of activity and interest as well as repetitive patterns of behavior. "In addition, there is a report of a patient with autism, ID and microcephaly who showed duplication with a size of 170 Kb containing PAOX, MTG1 and SPRN genes." (PMID 28357200, 2016).
cardiac hypertrophy (1 paper, 2021). "Further loss- and gain-of-function studies showed that MTG1 depletion worsened AB-induced hypertrophy, whereas MTG1 overexpression mitigated cardiac hypertrophy and dysfunction after the onset of AB." (PMID 35118147, 2021). "A novel role of mitochondrial GTPases 1 (MTG1), which was known to participate in mitochondrial ribosome assembly and translation, in pathological cardiac hypertrophy has recently been revealed." (PMID 35118147, 2021).
tumor (2 papers, 2021 to 2024). "Liu and Pan (2016) found that MTG1 played an important role in tumor induction or progression." (PMID 34239534, 2021).
Genetic disorders of (1 paper, 2021). "MTG6, pituitary, (20%) and MTG1, adrenal (19%) were slightly overrepresented among the individual responses, followed by MTG3, Genetic disorders of glucose and insulin homeostasis and MTG7, Sex Development and Maturation (12% each)." (PMID 33289690, 2021).
MTG1 also shares sentences with these, for which no sentence is quoted: cancer (1 paper); glioblastoma (1); heart diseases (1); hepatocellular carcinoma (1); malaria (1); microcephaly (1); mitochondrial disease (1); Stroke (1).